LINC02728 (long independently transcribed non-coding RNA 2728)
Gene: Long non-coding RNA gene on chromosome 11 (78,423,982 to 78,429,881, reverse strand). Ensembl gene ENSG00000251323.
Diseases named in the same sentence as LINC02728 in open-access papers:
LINC02728 is named in the same sentence as 1 disease in open-access papers, as found by Europe PMC text mining. Sharing a sentence is not in itself a finding about the gene and the disease. The quoted sentences say what the papers report.
neoplasm (1 paper, 2021). A benign or malignant tissue growth resulting from uncontrolled cell proliferation. "AC093642.1, AC243829.4, AL121748.1, LINC01614, and LINC02728 were expressed at higher levels in the higher neoplasm histological grade group." (PMID 35047016, 2021).